LGR5 (leucine rich repeat containing G protein-coupled receptor 5)
Diseases named in the same sentence as LGR5 in open-access papers (continued):
Sharing a sentence is not in itself a finding about the gene and the disease.
tumor (continued). "Indeed, lineage tracing studies revealed that LGR5+ cells were capable of tumor initiation and gave rise to all tumor cells." (PMID 34095127, 2021). "Stem cell markers, e.g., LGR5, have been shown to be present in the tumour buds." (PMID 34884696, 2021). "After the withdrawal of DT, the tumor was repopulated by Lgr5+ cells, reinitiating tumor growth." (PMID 33671641, 2021). "The RSPO2 anti-oncogenic role on CRC growth depends on the LGR5 presence on neoplastic cells: RSPO2 may function as a tumor suppressor by negatively regulating WNT signaling through a LGR5-dependent manner." (PMID 33562604, 2021). "Lgr5DTR-eGFP tumor organoids treated with the toxin collapsed after losing their stem cells and were unable to regrow upon toxin treatment maintenance, thus demonstrating the necessity of Lgr5+ stem cells." (PMID 33671641, 2021). "However, following exposure to inflammation and/or upon accumulating cooperating mutations, differentiated villus cells can re-express Lgr5 and ISC markers, and initiate tumours." (PMID 33673710, 2021). "Similarly, xenografted patient-derived organoids contain differentiated KRT20+ cells that can re-express LGR5 and fuel tumour regrowth." (PMID 33673710, 2021). "It remains to be investigated if Lgr5 signaling mechanisms play tumor-suppressive role in SCJ glandular stem cells, or Lgr5+ cells may be outcompeted by rapidly expanding Lgr5−CD44+ cells." (PMID 31901081, 2020). "The interrogation of clinical samples alongside in vitro and in vivo experiments in transgenic and PDX mouse models of BC demonstrates the potential of therapeutic intervention for TNBC patients by specifically targeting the tumorigenic LGR5+ tumor initiating cells." (PMID 32522170, 2020). "Interestingly, there was an inverse correlation between tumor and the relative size of the LGR5–GFP+ compartment at the end of the experiment, indicating that LGR5-expressing cells are probably more active in the tumor initiation period." (PMID 32327656, 2020). "The tumor numbers in the Lgr5/Arf1/Apc/IFNγ-KO and Lgr5/Arf1/Apc/Rag1-KO also significantly increased in comparison with those in the Lgr5/Arf1/Apc mice (Lgr5/Apc: 99.6 ± 8.9; Lgr5/Arf1/Apc: 41.0 ± 5.6; Lgr5/Arf1/Apc/Rag1-KO: 90.4 ± 11.0; Lgr5/Arf1/Apc/IFNγ-KO: 73.0 ± 9.5)." (PMID 31924786, 2020). "A speculative explanation could be that the tumors are derived from LGR5-positive stem cells, yet these cells are suppressed thereafter during tumor progression." (PMID 32327656, 2020). "Allograft tumor-bearing mice were first subjected to 5-FU (which increases the relative size of the LGR5+ compartment) followed by cessation of 5-FU therapy and start of DT treatment as to kill the LGR5+ cells." (PMID 32327656, 2020). "However, studies ablating leucine rich repeat containing G protein-coupled receptor 5 (LGR5)-positive stem cells have shown that they are rapidly replenished in primary tumours." (PMID 31906589, 2020). "Areas could be identified showing clear overlap between nuclear Lgr5 expression and frank nuclear atypia, indicating nuclear expression by carcinoma cells (vs. entrapped non-tumour cells)." (PMID 32894084, 2020). "Lgr5+ CSCs were specifically eradicated in situ, when localized based on the depth from the colon lumen, revealing the potential preventive efficacy of Lgr5-targeted therapy on tumor growth." (PMID 31947553, 2020). "It remains unclear how the profiles of distinct cell types along the differentiation axis in the intestine, e.g. Lgr5+ stem cells, absorptive progenitors or neuroendocrine cells, shape the phenotype of the resulting neoplasm." (PMID 33292279, 2020). "Moreover, after specific ablation of tumor Lgr5+ cells that have long-term self-renewal and differentiation capacities, differentiated KRT20+ cells can dedifferentiate into Lgr5+ cells." (PMID 32588148, 2020). "Importantly, accumulating data indicate that Lgr5 marks cancer cells with tumor initiating capacity, which possess characteristics of cancer stem cells (CSCs)." (PMID 32522170, 2020).
tumor (continued). "StemCO resembled LGR5-positive undifferentiated tumours in the lung, and diffCO had lumen structures composed of polarised cells that were similar to the ductal structures found in differentiated tumours in the liver." (PMID 32081957, 2020). "However, specific targeted ablation of LGR5+ cells in cancerous tissues revealed that the LGR5+ stem cell population is dispensable for primary tumour maintenance." (PMID 31906589, 2020). "Both DCLK1 and LGR5 were highly increased in tumour tissue compared with the matched controls." (PMID 32814764, 2020). "The utilization of anti-LGR5-ADC to target a smaller subset of potentially quiescent, tumorigenic LGR5+ tumor-initiating cells, which presumably are responsible for recurrence and metastatic progression, presents a novel line of therapy for high-grade ER− LGR5high BC." (PMID 32522170, 2020). "Lineage tracing studies in liver have shown that LGR5 stem cells aid in the formation of tumor." (PMID 32256979, 2020). "Thus, precise control of LGR5 expression is crucial for stem cell homeostasis and tumour suppression." (PMID 31867777, 2020). "However, upon removal of the inducer, the mitotically arrested, differentiated tumor cells restored the Lgr5+ CSC population and proliferated to regenerate the tumor." (PMID 33505918, 2020). "Using this minimally invasive fractionated PDT technique, we further reveal the role of Lgr5+ CSCs in tumor maintenance and proliferation, demonstrating the therapeutic potential of localized PDT for targeting Lgr5+ cells in sporadic tumor models while minimizing damage to off-target tissues." (PMID 31947553, 2020). "Taken together, these data suggest a role for Lgr5+ cells as tumor-initiating cells in ER− BC." (PMID 32522170, 2020). "Notably, tumor #2 exhibited only low LGR5 intestinal stem cell marker expression, but consisted of substantial amounts of enterocytes and secretory progenitor cells as depicted by high HES1 and SPDEF1 as well as moderate KLF4 expression, respectively." (PMID 33628739, 2020). "We also determined the tumor-initiating role of Lgr5 in lineage-tracing experiments." (PMID 32522170, 2020). "Moreover, these Lgr5+ cancer cells were functional SCs, as selective ablation of these cells by acute or chronic DT treatment in both organoid-derived and primary tumor-derived cells abolished organoid outgrowth." (PMID 32169167, 2020). "Treatment with a selective BRAFV600E inhibitor, vemurafenib, unexpectedly enriched the subpopulation of LGR5+ AM-EpiSCs in tumor 3D organoids, which may have explained therapeutic resistances and recurrences." (PMID 32382005, 2020). "Lgr5+ cells have been demonstrated to be the cells of origin of tumors, which may provide a feasible approach for effective targeted anti-tumor treatment through targeted elimination of Lgr5+ CSCs selectively." (PMID 31358061, 2019). "Thus this study examined Lgr5 expression on CRC samples and any association with clinicopathological characteristics of tumor." (PMID 31814939, 2019). "With regard to tumor progression, one-way ANOVA analysis identified a statistically significant association between the grade and stage of disease with TROY (p = 0.028) and LGR5 (p < 0.0001) expression, respectively." (PMID 30501144, 2019). "Hence, accumulating preclinical evidence have suggested the potential of targeting Lgr5 via Lgr5-targeted antibody-drug conjugates as effective novel therapeutics for tumor treatment." (PMID 31358061, 2019). "The increased expression of LGR5 correlated significantly with tumor regression." (PMID 31827644, 2019). "An increased expression of LGR5 in primary GC correlated significantly with tumor regression." (PMID 31827644, 2019). "Moreover, the incidence of tumor formation and the average number of papillomata per mouse also decreased markedly in Lgr5-Pten-/--β-catenin-/-mice." (PMID 31754399, 2019). "Additionally, deletion of Lgr5+ CSCs reduced tumor size, while removal of the apoptosis inducer resulted in the regrowth of tumors." (PMID 31317205, 2019).
tumor (continued). "We found that LGR-5 expression was higher in tumor tissues than in normal liver tissues, and that high LGR-5 expression possibly favored poor outcomes in HCC, especially in well/moderate differentiation grade, hepatitis C virus (HCV)-negative, and hepatitis B virus (HBV)-positive groups." (PMID 31126119, 2019). "In addition, up-regulation of Lgr5 in various tumor types with increased Wnt signaling has also been reported." (PMID 31417548, 2019). "Meanwhile, a more specific targeting of Lgr5-expressing tumor cells using double biomarkers may deserve further consideration and elucidation." (PMID 31358061, 2019). "Another study indicated that the tumor relapse was attributed to the dormancy of Lgr5+ cells and revealed that targeting Lgr5+ cells by inhibition of Wnt signaling (Wnt inhibitors, Lgk974) in combination with Vismodegib treatment resulted in regression of BCCs." (PMID 31438551, 2019). "The tumor cells of 88 (87.1%, valid n = 101) primary GCs, 54 (77.1%, valid n = 70) lymph node metastases, 10 (100%, valid n = 10) distant metastases, and 21 (87.5%, valid n = 24) pretherapeutic biopsies showed a cytoplasmic expression of LGR5." (PMID 31827644, 2019). "However, shortly after discontinuation of Lgr5+ cell depletion therapy, tumor growth resumes at similar growth rates as untreated control tumors." (PMID 30927915, 2019). "Specifically, ablation of LGR-5+ CSCs halted tumor growth, whereas the tumors resumed growth following the removal of the cell death inducers due to the re-emergence of CSCs from differentiated tumor cells." (PMID 31417869, 2019). "The higher Lgr5 levels in GC tumors with a high number of intratumor FoxP3+ Tregs observed in our study indicated that intratumor FoxP3+ Tregs may influence Lgr5 expression in tumor tissue." (PMID 31417548, 2019). "To investigate the hierarchy between these different tumour cell populations, marked by Notch1 or Lgr5 expression, we used the R26mTmG double fluorescent line, allowing us to distinguish between initially labelled cells (that we called “Mothers”) and their derived progeny." (PMID 30696875, 2019). "Tumor-derived WNT-secreting cells induce proliferation of WNT-responsive LGR5+ SCLC cells." (PMID 30948783, 2019). "Targeting niche factors that promote stemness and plasticity, such as BMI-1 and BCL-3, may be an effective way to target CRC stem cells in primary tumours and prevent reversion of differentiated cells to LGR5+ CSCs." (PMID 30792270, 2019). "LGR-5 is crucial in embryogenesis, tumor development, and tumor cell signal transduction." (PMID 31126119, 2019). "The removal of diphtheria toxin regenerated Lgr5+ CSCs and renewed tumor growth." (PMID 30934773, 2019). "Interestingly, the expression of LGR5 in the primary GCs correlated significantly with the Becker regression grade as well as with the percentage of vital tumor cells (p < 0.001 each; Supplementary)." (PMID 31827644, 2019). "Indeed, targeting LGR5+ cells with an antibody-drug conjugate has been shown to be safe and have potent tumor efficacy in CRC." (PMID 31417548, 2019). "We demonstrate a higher expression of Lgr5 in this tumor-normal comparison study." (PMID 31814939, 2019). "At 3 months after Cre activation, neoplasia had developed from Lgr5+ cells." (PMID 31772167, 2019). "The LGR-5 expression was higher in the tumor tissues than in the normal liver tissues." (PMID 31126119, 2019). "Lgr5 plays complicated and multifaceted roles during tumor progression." (PMID 31358061, 2019). "Elevated LGR5 expression has been correlated with increasing tumor grade and reduced OS." (PMID 29428975, 2018). "Moreover, tumor xenograft experiments in nude mice demonstrated that LGR5 has strong tumorigenicity." (PMID 29777575, 2018). "Furthermore, high Lgr5 expression in cells derived from mouse tumours correlates with strong upregulation of Wnt signalling." (PMID 29498662, 2018).
tumor (continued). "The complexity of CRC tumours, driven by factors such as tumour heterogeneity, tumour stage, cell of origin, stem cell hierarchies and the microenvironment mean that LGR5 function is likely to vary considerably, depending on the context in which it is assessed." (PMID 29844449, 2018). "Lgr5 expression was found in 82.4% (168/204) cases, significantly more common in neoplastic cells at the infiltrative front (n = 59.5%, 110/185) or at the expanding front (n = 36.4%, 59/162) than at the tumor center (n = 16.7%, 34/204; P < 0.01)." (PMID 30046385, 2018). "The first indication that LGR5 could have potential tumour suppressive effects in the gut came from studies showing a negative influence on Wnt signalling." (PMID 29844449, 2018). "Moreover, after suspension of diphtheria toxin treatment, LGR5+ cells rapidly reappear and tumor starts regrowing, supporting a model in which various types of LGR5− cancer cells can dedifferentiate and replenish the LGR5+ CSC pool." (PMID 29853913, 2018). "Taken together, such findings indicate that LGR5 expression may play a key role in mediating the survival and/or proliferative responses of tumours during malignant transformation." (PMID 29844449, 2018). "Studies have shown that LGR5 can promote tumor initiation, proliferation and invasion." (PMID 30208924, 2018). "Interestingly, Lgr5 gene expression has been reported previously to be dispensable for ex vivo tumor organoid maintenance." (PMID 30177706, 2018). "At the same time, the results further show that Lgr5 expression in CRC cells are more likely to migrate and invade normal tissues, especially in tumor budding cells, Lgr5 expression cells may have a higher potential to invasion and metastasis." (PMID 30046385, 2018). "Furthermore, recent studies demonstrating that CRC tumours contain LGR5+ subsets and retain a degree of normal tissue architecture has heightened translational interest." (PMID 29844449, 2018). "Therefore, classic quiescent stem cells have been studied as potential tumor-initiating cells, as well as more recently discovered actively dividing stem cells (either Lgr5+ or Lgr6+)." (PMID 29896477, 2018). "Previous studies have proven that LGR5 has a major role in enhancing tumor invasion and metastasis." (PMID 29777575, 2018). "Interestingly, our study also indicates that alterations in LGR5 expression for a short period of time is sufficient to reprogram tumor cell growth via Wnt signaling pathway that is in agreement with previous studies." (PMID 30089773, 2018). "A heterogeneous Lgr5 expression pattern was identified at different tumor sites of CRC." (PMID 30046385, 2018). "One study found that the selective ablation of LGR5+ CSCs in organoids led to tumor regression, while the proliferation of LGR5+ CSCs may contribute to tumor regrowth." (PMID 29700375, 2018). "Some functional studies have indicated that the LGR5 molecule could have a tumour suppressive role in CRC by limiting cell proliferation." (PMID 29844449, 2018). "Our findings indicate that LGR5 functions as a novel tumor oncogene in EOC, and may be a potential therapeutic target." (PMID 29777575, 2018). "To investigate whether enhanced tumor burden could enable detection of cfDNA, we employed the Lgr5-EGFP-IRES-CreERT2+/0;Apcfl/fl (Lgr5CreER-Apcfl/fl) mouse model of colon tumorigenesis." (PMID 30166531, 2018). "The study results confirmed that Lgr5 expression was significantly correlated to the tumor stage, and suggested that Lgr5 might play an important role in the CRC progression." (PMID 30046385, 2018). "Furthermore, in tumor xenograft experiments, the LGR5 knockdown group exhibited higher immunohistochemical staining for the epithelial marker, E‐cadherin, in addition to weaker expression of the mesenchymal‐associated molecule, N‐cadherin." (PMID 29777575, 2018).
tumor (continued). "The conflicting reports of the pro-oncogenic and tumour suppressive functions of LGR5 in CRC may originate from the inherent plasticity of normal stem cells and CSCs." (PMID 29844449, 2018). "Because Lgr5 is a well-known stem cell marker, Lgr5-expression tumor budding cells at the invasion front may have cancer stem cell characteristics, especially in those high-grade tumor budding cells, which remains to be further investigated." (PMID 30046385, 2018). "Notwithstanding, molecular mechanism of LGR5-mediated tumor metastases remains elusive." (PMID 30089773, 2018). "Similarly LGR5 (a surface G-protein coupled receptor) revealed its presence in OSE layer as well as cortex region of HG tumor." (PMID 30121075, 2018). "Therefore, the timing of any LGR5-directed therapy will be crucial for its long-term efficacy, and tumour stage-specific assessments of LGR5 therapies would be useful within in vivo models of CRC metastases." (PMID 29844449, 2018). "Taken together, LGR5 and canonical signaling seem to be of great importance for the expansion of NB from tumor stem cells, and may serve as a therapeutic target in NB." (PMID 29058015, 2018). "Moreover, LGR5 expression through its downstream Wnt signaling pathway promotes tumor cell proliferation, especially in breast and cervical cancers." (PMID 30089773, 2018). "These LGR5 +cells play critical roles as CSCs in tumor development." (PMID 30250044, 2018). "However, the ability of LGR5− CRC cells to rapidly reacquire LGR5 expression implies there are specific phases of tumour growth where LGR5 is important, which is evident during metastatic progression and drug/radiation exposure." (PMID 29844449, 2018). "The gene expression of ABCB5 in comparison to CD133 (molecule for identifying cancer initiating cells), Lgr5 (an intestinal stem cell marker) as well as Cytokeratin (CK) 20 (terminally differentiated tumor cells of epithelial origin) in these cells was evaluated." (PMID 34221246, 2017). "The scaling pattern of the LGR5+ cell output is compatible with the hypothesis that tumor growth is largely the result of LGR5+ cell activity." (PMID 28468934, 2017). "Lgr5 is involved in metastasis dissemination and CSCs plasticity, more than in tumor maintenance." (PMID 29354056, 2017). "ABCB5 and Lgr5 and to lesser extent CD133 and CK20 genes were significantly expressed in the analyzed cells from bone marrow aspirates while only ABCB5 and Lgr5 were significantly negative associated with tumor progress and overall survival." (PMID 34221246, 2017). "LGR5 is crucial for tumor development and tumor cell signal transduction." (PMID 28881613, 2017). "Interestingly, these findings were fully recapitulated in organoids in vitro, suggesting that Lgr5+ cell rescue is independent from tumor stroma." (PMID 28559443, 2017). "Based on our data, we suggest the following mechanism of tumor progression in the small intestine: original tumors are polyclonal; then, a single Lgr5- or Bmi1-positive cell proliferates and replaces other cells by clonal competition, resulting in the formation of large-size monoclonal tumors." (PMID 28176811, 2017). "Finally, to assess the capacity of these tumor cell populations to propagate the disease to mice, we inoculated 200 or 1,000 LGR5‐EGFP+ or LGR5‐EGFP− epithelial tumor cells isolated from xenografts into secondary hosts." (PMID 28468934, 2017). "Furthermore, knockdown of LGR5 suppressed the tumor formation incidence in NOD-SCID mice in both Huh-7 and MHCC-97L." (PMID 28455968, 2017). "Allograft tumours showed strong expression of the stem cell markers Lgr5 and CD44v6." (PMID 28622298, 2017).